ENSG00000202283
Synonyms: LOC124900225
Gene: Small nucleolar RNA gene on chromosome 6 (103,583,135 to 103,583,268, forward strand). Ensembl gene ENSG00000202283.
Gene Ontology:
Biological process: RNA processing
Cellular component: nucleolus
Homologues: Orthologues: mouse Gm22772 (63% identical). Paralogues in human: SNORA33 (83% identical).